CBFA2T3 (CBFA2/RUNX1 partner transcriptional co-repressor 3)
Description:
Transcriptional corepressor which facilitates transcriptional repression via its association with DNA-binding transcription factors and recruitment of other corepressors and histone-modifying enzymes. Can repress the expression of MMP7 in a ZBTB33-dependent manner. Reduces the protein levels and stability of the transcriptinal regulator HIF1A; interacts with EGLN1 and promotes the HIF1A prolyl hydroxylation-dependent ubiquitination and proteasomal degradation pathway. Contributes to inhibition of glycolysis and stimulation of mitochondrial respiration by down-regulating the expression of glycolytic genes including PFKFB3, PFKFB4, PDK1, PFKP, LDHA and HK1 which are direct targets of HIF1A. Regulates the proliferation and the differentiation of erythroid progenitors by repressing the expression of TAL1 target genes (By similarity). Plays a role in granulocyte differentiation. Isoform 2 functions as an A-kinase-anchoring protein.
Synonyms: MTG16; MTGR2; ZMYND4; RUNX1T3; ETO2
Tractability: PROTAC: ubiquitination databases record sites on it.
Gene: Protein-coding gene on chromosome 16 (88,874,858 to 88,977,207, reverse strand). Ensembl gene ENSG00000129993.
Subcellular location: Nucleus (Isoform 1); Nucleus, nucleolus; Nucleus, nucleoplasm (Isoform 2); Golgi apparatus membrane
Subcellular location (Human Protein Atlas): Nucleoplasm
Gene Ontology:
Molecular function: protein binding; transcription corepressor activity
Biological process: granulocyte differentiation; negative regulation of cell population proliferation; negative regulation of DNA-templated transcription; negative regulation of glycolytic process; negative regulation of transcription by RNA polymerase II; positive regulation of proteasomal ubiquitin-dependent protein catabolic process; regulation of aerobic respiration; response to hypoxia; DNA-templated transcription
Cellular component: Golgi membrane; nucleoplasm; nucleus; nucleolus
Genetic constraint (gnomAD): Loss-of-function variants: 29 observed, 41.3 expected, observed/expected ratio (o/e) 0.7, 90% interval 0.52 to 0.96. The synonymous counts are far from expectation, so gnomAD's model fits this gene poorly and the ratio says little. Missense variants: 1,009 observed, 779.71 expected, observed/expected ratio (o/e) 1.29, 90% interval 1.23 to 1.36. Synonymous variants: 505 observed, 348.34 expected, observed/expected ratio (o/e) 1.45, 90% interval 1.35 to 1.56.
Cancer hallmarks: change of cellular energetics (promotes); suppression of growth (promotes)
Homologues: Orthologues: chimpanzee CBFA2T3 (99% identical), macaque CBFA2T3 (96% identical), dog CBFA2T3 (85% identical), mouse Cbfa2t3 (84% identical), rat Cbfa2t3 (83% identical), guinea pig CBFA2T3 (82% identical), pig CBFA2T3 (81% identical), zebrafish cbfa2t3 (66% identical), tropical clawed frog cbfa2t3 (65% identical), Drosophila melanogaster nvy (31% identical). Paralogues in human: RUNX1T1 (66% identical), CBFA2T2 (53% identical).
Diseases named in the same sentence as CBFA2T3 in open-access papers:
CBFA2T3 is named in the same sentence as 49 diseases in open-access papers, as found by Europe PMC text mining. Sharing a sentence is not in itself a finding about the gene and the disease. The quoted sentences say what the papers report.
leukemia (23 papers, 2007 to 2025). A malignant (clonal) hematologic disorder, involving hematopoietic stem cells and characterized by the presence of primitive or atypical myeloid or lymphoid cells in the bone marrow and the blood. "Runt Related Transcription Factor 1 (RUNX1) and Core-Binding Factor Runt Domain Alpha Subunit 2 Translocated To 3 (CBFA2T3, ETO2, MTG16) are master regulators of hematopoiesis and are implicated in leukemia." (PMID 33743795, 2021). "Cbfa2t3 was the most dramatically down-regulated gene in placenta; CBFA2T3 is clinically associated with several types of human leukemia." (PMID 30013175, 2018). "Examples of hematopoietic genes are Kit, encoding the receptor for stem cell factor, and Cbfa2t3, encoding a core-binding factor whose ortholog in humans is rearranged in some leukemias." (PMID 25319994, 2014). "In summary, while CBFA2T3::GLIS2 leukemia remains a difficult-to-treat disease, we have validated JAK2 as a selective dependency offering a new possibility for precision medicine in this very high-risk AML subset." (PMID 40470252, 2025). "CBFA2T3, also known as RUNX1T3, MTG16, and ETO2, encodes a transcription corepressor and has been linked to maintenance of hematopoietic stem cell stemness, expansion of leukemia stem cells, AML relapse, and inhibition of myeloid differentiation." (PMID 40763310, 2025). "On the one hand, the introduction of CBFA2T3::GLIS2 into murine bone marrow is insufficient to induce overt leukemia in mice." (PMID 37325571, 2023). "Targeting CBFA2T3 in leukemia, especially acute lymphoblastic leukemia that expresses the E2A-Pbx1 fusion protein, is also supported by an increasing body of evidence." (PMID 36291849, 2022). "GLIS2 has been proposed as an oncogenic gene in leukemia, in which chromatin translocation causes the fusion of GLIS2 with CBFA2T3 and led to GLIS2 overexpression, and its mutation is linked with nephronophthisis in human and mice." (PMID 32483180, 2020). "Within this dataset, genes such as CBFB, SEPTIN9, CBFA2T3, CD1A, and ERG have been previously reported to be closely associated with leukemia development and progression. qPCR analysis further confirmed the reduced expression levels of these genes in IRF2BP2‐knockdown cells." (PMID 39454110, 2024). "Notably, the ETO-family transcriptional corepressors, including ETO (also known as RUNX1T1), ETO2 (also known as CBFA2T3) and MTGR1 (also known as CBFA2T2), are all involved in leukemia-causing chromosomal translocations." (PMID 36158200, 2022). "The frequent occurrence of the CBFA2T3::GLIS2 fusion in M7-type leukemia may be attributed to the enhanced BMP (bone morphogenetic protein) signaling which may directly contribute to megakaryocytic differentiation in leukemia cells." (PMID 41294667, 2025). "Additionally, the upregulated DEGs in Mx1-CreCbfb+/56M cells also positively correlated with CHYLA_CBFA2T3_TARGETS_UP and negatively correlated with CHYLA_CBFA2T3_TARGETS_DN, suggesting a critical role for CBFA2T3 during leukemia initiation in Mx1-CreCbfb+/56M mice." (PMID 40763310, 2025). "Overall, multiple molecular alterations may contribute to the phenotype of CBFA2T3::GLIS2 leukemia." (PMID 37325571, 2023). "Interestingly, leukemia-associated pathways that were regulated by ERG in murine fetal liver-derived HSPCs (Hoxa9-Meis1, CBFA2T3, and repression of myeloid differentiation genes) were ranked at the leading edge of gene sets that were significantly perturbed after HDAC3 inhibition." (PMID 37735473, 2023). "CBFA2T3 participates in hemopoietic stem cell (HSC) self-renewal and differentiation, megakaryocyte-erythrocyte progenitor development, and leukemia stem cell (LSC) expansion." (PMID 37325571, 2023). "In an endothelial cell coculture system, the expression of CBFA2T3::GLIS2 transforms human cord blood hematopoietic stem and progenitor cells (HSPCs) and leads to highly aggressive leukemia in mice." (PMID 37325571, 2023).
leukemia (continued). "Another pro-survival protein BCL-xL was also identified as a potential therapeutic vulnerability in erythroid and megakaryocytic lineage leukemias, including in the M07e AMKL cell line harboring CBFA2T3::GLIS2." (PMID 37325571, 2023). "We demonstrated that one mechanism by which CBFA2T3 and RUNX1 promote leukemogenesis or maintain leukemia is by controlling cell proliferation." (PMID 33743795, 2021). "To date, the exact mechanisms by which the CBFA2T3::GLIS2 fusion confers leukemia aggressiveness and chemoresistance are not completely understood." (PMID 40470252, 2025). "Our findings unveil the role of CBFA2T3 also as a transcriptional activator for RUNX1 in human PreB lymphoblasts, and demonstrate the existence of a new RUNX1 and CBFA2T3 driver-loop in ETV6-RUNX1 BCP-ALL leukemia." (PMID 33743795, 2021). "Furthermore, CD56+CD45−-cells are always suggestive of BM metastases of various solid tumors, and even BM differentiation between leukemia and nonhematopoietic tumors is one of the main challenges in CBFA2T3::GLIS2-positive AMKL diagnosis." (PMID 40565358, 2025). "The role of miRNA changes in leukemia initiation by CBFA2T3::GLIS2 is not well defined." (PMID 37325571, 2023). "Studies have indicated that CBFA2T3::GLIS2 is the most common chimeric oncogene in non-DS-AMKL, representing the highly aggressive nature of leukemia." (PMID 40547921, 2025). "CBFA2T3::GLIS2 is not specific to AMKL and occurs in diverse morphologic subtypes of de novo AML (except for acute promyelocytic leukemia (APL) and leukemia with erythroid differentiation), overall found in approximately 8.4% of cytogenetically normal AML cases." (PMID 37325571, 2023).
acute myeloid leukemia (16 papers, 2008 to 2025). Acute myeloid leukemia (AML) is a group of neoplasms arising from precursor cells committed to the myeloid cell-line differentiation. "Many studies have shown that CBFA2T3 is associated with acute myeloid leukemia." (PMID 38786053, 2024). "We recently discovered FOLR1 to be expressed in a highly refractory infant acute myeloid leukemia (AML) driven by the CBFA2T3::GLIS2 fusion." (PMID 40919994, 2025). "CBFA2T3 expression levels are elevated in lymphoid and myeloid based cell lines, and genetic CBFA2T3 fusion with RUNX1 or GLIS2 accelerates acute myeloid leukemia and megakaryoblastic leukemia." (PMID 38786053, 2024). "showing that downregulation of CBFA2T3 arrests G1/S cell cycle progression and attenuates in vitro and in vivo proliferation of acute myeloid leukemia cells." (PMID 33743795, 2021). "CBFA2T3 depletion arrests cell cycle progression in acute myeloid leukemia cell lines and CD34 + hematopoietic stem and progenitor cells (HSPC)." (PMID 33743795, 2021). "In acute myeloid leukemia, CBFA2T3 can be a translocation partner of RUNX1, producing a chimeric protein with breakpoints usually between exons 1 and 2, or exons 3 and 4 of CBFA2T353." (PMID 30926794, 2019). "MTG8 and MTG16 (CBFA2T3) were originally identified as targets of chromosomal translocations in acute myeloid leukemia, suggesting an important role in cellular growth and development." (PMID 23251453, 2012). "CBFA2T3, a factor in human acute myeloid leukemia, promotes myeloid differentiation." (PMID 35391799, 2022). "CBFA2T3::GLIS2 fusion positive pediatric acute myeloid leukemia (AML) remains one of the worst prognostic AML subgroups." (PMID 40470252, 2025). "CBFA2T3 is a close relative of ETO, which is a target of the recurrent AML1-ETO translocation that occurs in acute myeloid leukemia." (PMID 20052266, 2010). "CBFA2T3 (MTG16), CBFA2/RUNX1 Partner Transcriptional Co-Repressor 3, has not been clearly studied in lung cancer although the CBFA2T3-GLIS2 fusion transcript is well proven as a novel common feature in pediatric cytogenetically normal acute myeloid leukemia (AML)." (PMID 34540825, 2021).
breast carcinoma (13 papers, 2005 to 2024). "Loss of heterozygosity in the genomic region encompassing CBFA2T3 gene occurs in half of all breast cancer cases and in vitro data suggest its tumor suppression function." (PMID 25749032, 2015). "In cancer studies, CBFA2T3 has anti-cancer properties in azoxymethane/dextran sulfate sodium-induced colon tumorigenesis and anti-proliferative activity in human breast cancer cells." (PMID 38786053, 2024). "In breast cancer, the expression of CBFA2T3 is lower in normal breast tissue compared to the primary tumors, consistent with our finding in the clusters of epithelial and endothelial cells by analyzing single-cell RNA-sequencing data." (PMID 34540825, 2021). "In fact, loss of heterozygosity (LOH) at the CBFA2T3 locus (16q24.3) is observed in an estimated 36–67% of ductal carcinomas, and ectopic overexpression of MTG16 in breast cancer cell lines inhibits their colony formation." (PMID 29358956, 2017). "Aberrant methylation of CBFA2T3 promoter has been found in breast cancer tissue compared to normal." (PMID 26039411, 2015). "In breast cancer, Med19 may promote cell proliferation by regulating CBFA2T3/HEB expression." (PMID 28125713, 2017). "CBFA2T3 overexpression suppresses MED19 levels and inhibits breast cancer cell proliferation in MCF-7 and MDA-MB-231 cells." (PMID 38786053, 2024). "We studied CBFA2T3, FANCA, FBXL8, LRRC29, TERF2 and TERF2IP, six potential breast cancer TSG candidate genes located on the long arm of chromosome 16, which is involved in LOH in more than 50% of breast cancer cases." (PMID 16280054, 2005). "The most statistically significant canonical cancer gene affected by SVs in TWT melanomas was CBFA2T3, which was not altered in any of the other genomic subtypes (Fisher’s exact, OR = infinity, 95% CI = 5.69–infinity, P = 1.3 × 10–4) and is a putative tumor suppressor in breast cancer." (PMID 38758740, 2024).
acute megakaryoblastic leukemia (7 papers, 2017 to 2026). Acute megakaryoblastic leukemia (AMKL) is a form of acute myeloid leukemia (AML) that occurs predominantly in childhood and particularly in children with Down syndrome (DS-AMKL). "This study retrospectively analyzed the clinical manifestations, genetic characteristics, treatment courses, and prognoses of patients with pediatric acute megakaryoblastic leukemia (AMKL) with CBFA2T3::GLIS2 fusion treated at the Institute of Hematology, Chinese Academy of Medical Sciences." (PMID 41991315, 2026). "Several studies demonstrated that a cryptic inversion of chromosome 16 that fuses CBFA2T3 to GLIS2, is frequently (25–30%) associated with a pediatric non-Down’s syndrome (non-DS) acute megakaryoblastic leukemia (AMKL) with poor prognosis." (PMID 35681527, 2022).
Down syndrome (5 papers, 2017 to 2025). "CBFA2T3::GLIS2, resulting from cryptic inversion of chromosome 16, is the most frequent chimeric oncogene in non-Down syndrome AMKL." (PMID 40565358, 2025). "In non-Down syndrome children with AMKL, CBFA2T3::GLIS2 is the most frequent chimeric oncogene identified to date." (PMID 40565358, 2025).
lung carcinoma (5 papers, 2012 to 2024). "CBFA2T3 is also a tumor suppressor in lung cancer and can serve as an independent prognostic marker for LUAD36." (PMID 38555384, 2024). "CBFA2T3 has been reported as a tumor suppressor in lung cancer and can be an independent prognostic marker in LUAD." (PMID 35265614, 2022).
acute erythroid leukemia (3 papers, 2013 to 2023). An acute myeloid leukemia characterized by a predominant immature erythroid population. "The role of NFI members in AML have been very limited where only the NFIA fusion protein NFIA/CBFA2T3 has been reported in acute erythroid leukemia." (PMID 36572750, 2023).
acute lymphoblastic leukemia (3 papers, 2017 to 2024). Leukemia with an acute onset, characterized by the presence of lymphoblasts in the bone marrow and the peripheral blood. "Increased expression of CBFA2T3 has been observed in B Cell Precursor Acute Lymphoblastic Leukemia (BCP-ALL), and the truncation protein of CBFA2T3 significantly decreases BCP-ALL lymphocyte proliferation." (PMID 38382106, 2024).
medulloblastoma (3 papers, 2023 to 2025). A malignant, invasive embryonal neoplasm arising from the cerebellum. "CBFA2T2 and CBFA2T3 are recurrently mutated in Group 4 medulloblastoma, a tumour hypothesized to originate in the rhombic lip subventricular zone." (PMID 41279093, 2025). "For example, the CBFA complex, which includes CBFA2T3, is suggested to play a critical role in tumor development through its interactions with epigenetic modifiers, contributing to the pathogenesis of medulloblastoma." (PMID 37745846, 2023). "Mutually exclusive mutations in group 4 medulloblastomas could be attributed to the effect of the core binding factor (CBFA) and include CBFA2T2, CBFA2T3, PRDM6, UTX, and OTX2 genes." (PMID 36829544, 2023).
acute leukemia (2 papers, 2012 to 2021). A clonal (malignant) hematopoietic disorder with an acute onset, affecting the bone marrow and the peripheral blood. "CBFA2T3 and RUNX1 genes are also RUNX1 targets in myeloid cells and in mixed-phenotype acute leukemia." (PMID 33743795, 2021).
B-cell lymphoma (2 papers, 2015 to 2022). "In this study, we also examined the roles of the transcriptional corepressor Cbfa2t3, a previously reported Lmo2-interacting molecule in B-cell lymphoma and the erythrocytic lineage." (PMID 36126774, 2022). "CBFA2T3 is also found in IGH chromosomal translocations in pediatric B-cell lymphoma." (PMID 26039411, 2015).
breast tumor (2 papers, 2004 to 2020). "CBFA2T3 gene expression levels are aberrant in breast tumor cell lines and the CBFA2T3B isoform is a potential tumor suppressor gene." (PMID 15301688, 2004). "It was recently demonstrated that CBFA2T3 expression levels are aberrant in breast tumor cell lines." (PMID 15301688, 2004). "The CBFA2T3 locus located on the human chromosome region 16q24.3 is frequently deleted in breast tumors." (PMID 15301688, 2004). "It was recognized that aberrant promoter methylation might be the mechanism responsible for the altered expression of CBFA2T3 in breast tumors." (PMID 15301688, 2004). "Gfi1 also interacts with CBFA2T3, a transcriptional repressor that belongs to the ETO family of proteins and has been proposed as a putative breast tumor suppressor gene." (PMID 32630147, 2020).
lung adenocarcinoma (2 papers, 2022 to 2024). A carcinoma that arises from the lung and is characterized by the presence of malignant glandular epithelial cells. "CBFA2T3 gene expression is elevated in lung adenocarcinoma cell lines A549 and H2122, and CBFA2T3 has been identified as potential tumor antigens for mRNA vaccine development in lung adenocarcinoma." (PMID 38786053, 2024). "In the current study, we screened for genes associated with the prognosis of patients with lung adenocarcinoma and positively correlated with antigen-presenting cell infiltration and identified KLRG1 and CBFA2T3 as potential tumor antigens for mRNA vaccines in lung adenocarcinoma (LUAD)." (PMID 35265614, 2022).
B-cell acute lymphoblastic leukemia (1 paper, 2025). A neoplasm of lymphoblasts committed to the B-cell lineage, typically composed of small to medium-sized blast cells. "We analyzed the function of PAX5::CBFA2T3 (PAX5‐C), a fusion protein found in B‐cell acute lymphoblastic leukemia." (PMID 40643079, 2025).
Burkitt lymphoma (1 paper, 2019). A rare form of malignant mature B-cell non-Hodgkin lymphoma. "This suggests that CBFA2T3, which is dysregulated in BL, via translocation, differential splicing, and differential methylation, belongs to an ID3-TCF3-CBFA2T3 network important to Burkitt lymphomagenesis." (PMID 30926794, 2019).
chondrosarcoma (1 paper, 2015). A malignant cartilaginous matrix-producing mesenchymal neoplasm arising from the bone and soft tissue. "We found that the CBFA2T3 protein is undetectable or reduced in majority of OS samples (80.6% ± 7.9%) and chondrosarcoma samples (69.6% ± 17.4%)." (PMID 25749032, 2015).
cognitive decline (1 paper, 2019). "Taken together, we reasoned that CBFA2T3 might affect the neurogenesis process and AD-related cognitive decline." (PMID 31370031, 2019).
dementia (1 paper, 2023). Loss of intellectual abilities interfering with an individual's social and occupational functions. "Of these significantly positively correlated autoantibodies, five were differentially expressed in dementia and included CL1A, CBFA2T3, PKLR, APPL1, and NUDT2, whilst two were dysregulated in MCI including ABI1 and NUDT2." (PMID 38107644, 2023).
diffuse large B-cell lymphoma (1 paper, 2021). "Finally, in B-cell lineage, and in Diffuse Large B-cell Lymphoma in particular, CBFA2T3 is reported to be part of the LMO2 complex regulating kinetochore function, chromosome assembly, and mitosis." (PMID 33743795, 2021).